Y_RNA (Y RNA )
Gene: Miscellaneous RNA gene on chromosome 12 (95,617,689 to 95,617,786, forward strand). Ensembl gene ENSG00000212448.
Homologues: Orthologues: chimpanzee Y_RNA (100% identical). Paralogues in human: Y_RNA (87% identical), RNY1 (86% identical), Y_RNA (86% identical), Y_RNA (83% identical), Y_RNA (82% identical), RNY1P5 (81% identical), RNY1P7 (81% identical), Y_RNA (81% identical), Y_RNA (80% identical), RNY1P11 (79% identical), Y_RNA (79% identical), RNY1P1 (78% identical), and 90 more.